RNU6-690P (RNA, U6 small nuclear 690, pseudogene)
Gene: Small nuclear RNA gene on chromosome 8 (95,599,114 to 95,599,219, forward strand). Ensembl gene ENSG00000202112.
Homologues: Orthologues: chimpanzee U6 (100% identical), macaque U6 (98% identical), dog U6 (83% identical), guinea pig U6 (83% identical), pig U6 (80% identical), rabbit U6 (78% identical). Paralogues in human: RNU6-1145P (89% identical), RNU6-1316P (87% identical), RNU6-1067P (86% identical), RNU6-1181P (86% identical), RNU6-480P (86% identical), RNU6-1060P (85% identical), RNU6-116P (85% identical), RNU6-16P (85% identical), RNU6-38P (85% identical), RNU6-393P (85% identical), RNU6-46P (85% identical), RNU6-890P (85% identical), and 1285 more.